YAP1 (Yes1 associated transcriptional regulator)
Diseases named in the same sentence as YAP1 in open-access papers (continued):
Sharing a sentence is not in itself a finding about the gene and the disease.
squamous cell carcinoma (17 papers, 2016 to 2024). A carcinoma arising from squamous epithelial cells. "The oncogene YAP1 was found to be amplified in human squamous cervicalmalignancies, and its overexpression in cervical epithelial cells caused squamous cell carcinoma to grow in a mouse model." (PMID 37886144, 2023). "In the prevention of squamous cell carcinoma yes-associated protein 1 (YAP1) and ∆Np63α are an important target of SFN." (PMID 30445746, 2018). "YAP and TAZ encoding genes (YAP1 and WWTR1, respectively) are frequently amplified in squamous carcinoma and ample evidence has suggested the oncogenic role of YAP/TAZ across multiple cancer types." (PMID 37150829, 2023). "Yes-associated protein-1 (YAP-1) is a Hippo system transcription factor, which serves as an oncogene in squamous cell carcinoma, and several solid tumors when the Hippo pathway is dysregulated." (PMID 37476371, 2023). "The expression level of LINC010148 can be elevated by USF1, and LINC010148 interacts with TAF15 to bind to the promoter of YAP1, which further triggers the development of squamous carcinoma." (PMID 34285657, 2021). "The ΔNp63 isoform regulates translocation of YAP1 in squamous carcinoma and in response to DNA damage." (PMID 33803512, 2021). "Intriguingly, mutually exclusive copy number gains of chromosome 3q and 11q22 (where YAP1 is mapped to) have been reported in squamous cell carcinoma and consistently, YAP1 and WWTR1 amplification were also found to be mutually exclusive in HNSCC." (PMID 32990596, 2020). "We have shown that YAP1 and ∆Np63∆ are overexpressed in squamous cell carcinoma and the level of these pro-survival proteins is further markedly enriched in ECS cells." (PMID 29088716, 2017). "The regulation of YAP1 through Sox2 could be indirect in squamous cell carcinoma, as Sox2 antagonizes WWC1 to drive YAP1 activation." (PMID 36833308, 2023). "Thus, targeting YAP1 and ∆Np63α is an important potential strategy for reducing cancer stem cell survival in squamous cell carcinoma." (PMID 29088716, 2017). "Differential diagnosis with squamous cell carcinoma is difficult, although NUT expression and YAP1 fusion products can be very useful for diagnosis." (PMID 38891945, 2024). "In contrast, YAP1 is expressed in NSCLC, including adenocarcinoma, squamous cell carcinoma, and a proportion of large cell neuroendocrine carcinomas." (PMID 38180245, 2024). "This was mainly attributed to the elevated proportion of cases with YAP1/WWTR1 genomic amplification and high expression heterogeneity of YAP/TAZ target gene signature, which correlated with decreased overall survival of patients with squamous cell cancers." (PMID 36551696, 2022). "Furthermore, this study demonstrated that the frequent amplification of YAP1 and TAZ occurred in a mutually exclusive manner in HNSC and CESC, in addition to delineating the molecular mechanism of TAZ being involved in the regulation of squamous cell carcinoma progression." (PMID 35865173, 2022). "Thus, it was implied that crosstalk between YAP1 and CDK6 seems to play a pivotal role in conferring radiation resistance and targeting both YAP1 and CDK6 could be a useful therapeutic strategy to treat both esophageal adenocarcinoma and squamous cell carcinoma." (PMID 33665161, 2020).
Sepsis (16 papers, 2022 to 2025). Sepsis is defined as life-threatening organ dysfunction caused by a dysregulated host response to infection. "Yes-associated protein 1 (YAP1), a Hippo pathway regulator, modulates ferroptosis-related genes and mitigates sepsis-induced ALI/ARDS." (PMID 41383584, 2025). "Knocking down YAP1 in CLP-induced sepsis model mice was sufficient to exacerbate the ferroptotic death of hepatocytes and associated liver injury, while YAP1 overexpression in vitro within hepatocytes was sufficient to mitigate LPS-induced ferroptotic death." (PMID 40061452, 2025). "We discovered that the ferroptosis-related pathway was closely linked to the differentially expressed genes, and YAP1 was upregulated in sepsis-induced ALI models." (PMID 35979359, 2022). "YAP1 inhibits ferritinophagy-mediated ferroptosis in hepatocytes, and YAP1 deficiency aggravates sepsis-induced liver injury." (PMID 36182901, 2022). "Our in-vivo study found that YAP1 deficiency aggravated sepsis-induced lung pathological damage and produced Fe2+ overload and higher MDA levels as well as more ROS accumulation in YAP1f/f mice after CLP." (PMID 35979359, 2022). "YAP1 prevents ferroptosis driven by ferritin phagocytosis, offering protection against septic liver injury, while its deficiency worsens liver damage during sepsis." (PMID 39737174, 2024). "Based on these reports, our study aimed to investigate whether YAP1 was involved in pulmonary epithelial cell ferroptosis in response to LPS stimulation and to explore the underlying mechanism of ferroptosis in sepsis-induced ALI." (PMID 35979359, 2022). "Sepsis induced mouse cardiomyocytes apoptosis and cardiac dysfunction through activation of YAP1/Serpine1/caspase-3 pathway." (PMID 39308919, 2024). "In sepsis, YAP1/WWTR1 acts as a regulator, helping cells cope with excessive ROS generation and oxidative damage." (PMID 39737174, 2024). "Yap1 conditional knockout mice were used to confirm the role of Yap1‐related neuronal injury in sepsis‐induced SAE in vivo." (PMID 39400418, 2024). "In the current study, we noted that YAP1 conditional knockout aggravated sepsis-induced ferroptosis-like morphological changes, and produced more of ROS, MDA and Fe2+ production in liver tissues." (PMID 36182901, 2022). "To verify the involvement of YAP1 in sepsis-induced liver injury, we used the YAP1 liver-conditional knockout mice." (PMID 36182901, 2022). "Briefly, YAP1 played a pivotal role in ferroptosis suppression via regulating the ferroptosis mediator in sepsis-induced ALI." (PMID 35979359, 2022). "In conclusion, our results demonstrate the important participation of ferroptosis and YAP1 in the pathophysiology of sepsis-induced ALI." (PMID 35979359, 2022). "To verify the role of YAP1 with ferroptosis in sepsis-induced ALI in vivo, we used the YAP1 conditional knockout mice for further research." (PMID 35979359, 2022). "Further investigation should be expected to explore the accurate regulation of YAP1 in sepsis-induced pulmonary diseases targeting ferroptosis." (PMID 35979359, 2022). "Yap1 conditional knockout significantly aggravated learning and memory dysfunction, as well as hippocampal pathological damage, inflammatory response, ROS accumulation, mitochondrial fission and Fe2+ overload in sepsis mice induced after CLP." (PMID 39400418, 2024). "This study focused on the potential role of YAP1 in ferroptosis during sepsis." (PMID 36182901, 2022). "Herein, this study aimed to explore the involvement of ferroptosis in the etiopathogenesis of sepsis-induced acute lung injury (ALI) and demonstrate that YAP1 could disrupt ferritinophagy and moderate sepsis-induced ALI." (PMID 35979359, 2022). "In conclusion, our results demonstrate that YAP1 suppresses ferritinophagy- mediated ferroptosis via disruption of NCOA4–FTH1 reaction, thus attenuates sepsis-induced liver injury, which raises the possibility that YAP1 might be a potential therapeutic target of septic liver injury." (PMID 36182901, 2022).
Sepsis (continued). "Hence, given the protective role of YAP1 in promoting cell proliferation, we hypothesized that YAP1 exerted a protective effect in sepsis-induced liver injury." (PMID 36182901, 2022). "Hence, considering the protective role of YAP1 in promoting cell proliferation, we explored whether sepsis was a vital process in facilitating the ferroptosis of epithelial cells, which could be concerned with YAP1 activity." (PMID 35979359, 2022). "YAP1 in the Hippo pathway has been shown to alleviate lipopolysaccharide-induced ferroptosis and to significantly reduce ROS accumulation and intracellular free iron ion level in MLE-12 cells during sepsis-induced acute lung injury." (PMID 40959280, 2025). "YAP1 disrupted the NCOA4–FTH1 reaction and inhibited NCOA4-mediated ferritinophagy to prevent ferroptosis and subsequent mitochondrial ROS-related dysfunction in sepsis-induced ALI." (PMID 39161900, 2024). "These outcomes reminded us that ferroptosis participates in the genesis and development of sepsis-induced ALI, and YAP1 modulates the process by controlling Fe2+ and lipid peroxidation, which might provide a targeted strategy for mitigating sepsis-induced ALI." (PMID 35979359, 2022). "Taken together, these experimental data suggested that YAP1 could suppress FTH1 autophagic degradation mediated by NCOA4, which was crucial for protecting pulmonary epithelial cells from sepsis-induced ferroptosis." (PMID 35979359, 2022). "In this study, we unveiled that ferroptosis in pulmonary epithelial cells was generated in sepsis-induced ALI, and YAP1 may be a feasible protective agent that prevents ALI by inhibiting ferroptosis." (PMID 35979359, 2022). "As the signalling pathway of this study is too extensive, further study should be done to demonstrate the role of Yap1 and ferroptosis in SAE.In conclusion, our study demonstrated that sepsis could induce hippocampus ferroptosis via lipid peroxidation and increased iron load, which leads to SAE." (PMID 39400418, 2024). "However, the mechanism remains unclear, so we investigated the effect of Yap1 in SAE, which may provide a target strategy to alleviate sepsis‐induced SAE." (PMID 39400418, 2024). "As expected, YAP1 conditional knockout triggered the autophagy and promoted the degradation of ferritin in CLP-induced ALI, indicating that YAP1 might affect ferroptosis by mediating ferritinophagy in sepsis-induced ALI." (PMID 35979359, 2022).
supratentorial ependymoma (16 papers, 2018 to 2025). A high grade ependymoma that is located within the supratentorial brain. "For example, Yes1 associated transcriptional regulator (YAP1)–MAMLD1 fusions are restricted to supratentorial ependymoma (ST-EPN)." (PMID 35169893, 2022). "Supratentorial ependymoma, YAP1 fusion-positive, is a circumscribed ependymal tumor, which is characterized by fusions involving YAP1 gene (WHO Classification of Tumours Editorial Board, 2021)." (PMID 38544524, 2024). "Supratentorial ependymomas, YAP1 fusion-positive are rare, usually occurring in young children and MAMLD1 is the most frequent YAP1 gene partner." (PMID 37658995, 2024). "The ST-EPN-YAP1 subgroup is a less common type of supratentorial ependymoma and harbors YAP1-related fusions, found as YAP1-MAMLD1 and YAP1-FAM118B gene fusions." (PMID 33228790, 2020). "A small subset of pediatric supratentorial ependymomas harbor a YAP1-MAMLD1 fusion." (PMID 34008056, 2021). "YAP1 fusions are a key characteristic of one subgroup of supratentorial ependymomas and we hypothesize that these mutations may represent convergent evolution, producing similar phenotypic effects via a different mechanism." (PMID 29440180, 2018). "Supratentorial ependymomas (ST-EPNs) are predominantly characterized by common driver gene fusions such as ZFTA and YAP1 fusions." (PMID 38469231, 2024). "In the supratentorial compartment, there are two other groups with different molecular features, clinical characteristics and outcome, i.e., the supratentorial ependymoma ZFTA fusion-positive and the supratentorial ependymoma YAP1 fusion-positive." (PMID 35384591, 2022).
breast tumor (15 papers, 2014 to 2025). "Our results also demonstrated a significant association between high Ki-67 index and YAP1 positivity (p = 0.028), suggesting a potential link between YAP1 activity and proliferative capacity in breast tumors." (PMID 40731926, 2025). "Following these notions, our bioinformatic analysis between ERK1 and YAP1 signaling-related gene demonstrated that ERK1 levels were negatively associated with YAP1 signaling-related gene levels in breast tumors and cell lines." (PMID 31848326, 2019). "We therefore tested the function of Yap1 directly in primary breast tumors in a mouse model using gain-of-function and loss-of-function assays." (PMID 26695440, 2016). "By analysing YAP1 mRNA and protein expression in a large number of primary breast tumours, we show that increased YAP1 is associated with more aggressive tumours in ER- breast tumours whereas in ER+ tumours, decreased YAP1 expression correlates to aggressiveness." (PMID 24559095, 2014). "Has_circ_0005273 played an oncogenic effect in breast tumors by behaving like a sponge for tumor repressor miR-200a-3p, which inactivated the YAP1-Hippo signaling pathway." (PMID 37692482, 2024). "Retrospectively obtained 455 breast tumor samples at Gangnam Severance Hospital were examined for YAP1 expression by immunohistochemistry, and the clinical data were analyzed." (PMID 33718163, 2021). "Breast tumors from metastatic patients previously exposed to trastuzumab showed a high incidence of YAP1 (21%) and TAZ (24%) overexpression." (PMID 32365528, 2020). "Using a MMTV-Wnt1 mouse model of breast tumor, further functional assays implicate a critical role for Yap1 in regulating the self-renewal of TICs within this mouse tumor." (PMID 26695440, 2016). "To knockout Yap1 (Yap1-ko) in breast TICs, which were sorted from Yap1-flp breast tumors in vitro, we infected these cells with adenovirus-Cre." (PMID 26695440, 2016). "Collectively these results demonstrate that Yap1 activation was required for the expansion of breast tumor cells and the self-renewal of breast TICs in vitro and in vivo." (PMID 26695440, 2016). "In the present study, starting with high-throughput RNA-seq data, we identified Yap1 by its specific expression and activation within breast tumor TICs." (PMID 26695440, 2016). "Using a primary mouse breast tumor model, we show that ectopic expression of active Yap1 increases TIC self-renewal and TIC frequency within these tumors, while the loss of endogenous Yap1 disrupts TIC self-renewal and decreases TIC frequency." (PMID 26695440, 2016). "To study Yap1 function within these tumors in vivo, we continuously injected tamoxifen into mice bearing breast tumors for 2 weeks, and then we waited for another 3 weeks to harvest these tumors." (PMID 26695440, 2016). "After identifying TICs in spontaneous breast tumors of the MMTV-Wnt1 mouse model, we confirmed the specific expression and activation of Yes-associated protein 1 (Yap1) within TICs." (PMID 26695440, 2016). "Next, we asked whether Yap1 activation was required for breast tumor cell growth and self-renewal of breast TICs." (PMID 26695440, 2016). "Notably, Yap1 expression was selectively correlated with survival outcomes in basal breast tumor patients." (PMID 26695440, 2016). "Consequently, the loss of Yap1 led to a dramatic growth disadvantage of TICs both in vivo and in vitro, and it significantly decreased TIC frequency within these breast tumors." (PMID 26695440, 2016). "To our knowledge, we are the first to test Yap1 function in TICs from primary breast tumor instead of from a cell line, as the former can more closely reflect the true features of the TICs from human breast tumors." (PMID 26695440, 2016). "A conditional knock-out mouse was reconstructed to generate Yap1 knock-out breast tumors." (PMID 26695440, 2016).
breast tumor (continued). "By examining a premenopausal primary breast tumour material randomised to either tamoxifen or control treatment, we found that absent YAP1 protein expression was associated with impaired tamoxifen response." (PMID 24559095, 2014). "Moreover, YAP1 expression in TMAs with different BC subtypes also showed its expression was higher in TNBC subtypes, and its expression level was closely associated with high stage of breast tumors." (PMID 35102250, 2022). "We found that Yap1 could independently predict prognosis in 2,072 breast tumor patients." (PMID 26695440, 2016). "Finally, to directly test whether a Yap1-ko could inhibit tumor initiating ability within breast tumors, we performed LDA in vivo." (PMID 26695440, 2016). "Therefore, our study confirms that Yap1 is a potential drug target for these human breast tumors." (PMID 26695440, 2016). "Yap1 is important in breast tumor growth, progression and metastasis, and could be a potential therapeutic target for specifically eliminating breast TICs, thus greatly improving the prognosis of human breast tumors." (PMID 26695440, 2016). "The expression levels of MDM4, MDM2, YAP1, and YPEL3 in human breast tumor samples were investigated compared to normal samples using TNM plot analysis." (PMID 39345743, 2024). "In breast tumors, for example, high expression of the ZEB1/YAP1 target genes results in a significantly shorter relapse-free and overall survival." (PMID 36936987, 2023). "These ESR1 fusions transcripts, ESR1-e6>YAP1 and ESR1-e6>PCDH11X, were identified in patients with metastatic ER+ breast tumors that were pan-endocrine therapy resistant." (PMID 31106278, 2019). "Taken together, active Yap1 could promote TIC self-renewal and increase TIC frequency in breast tumors." (PMID 26695440, 2016).
oral squamous cell carcinoma (15 papers, 2007 to 2023). "Overexpression of common genes associated with tobacco-induced oral squamous cell carcinoma (OSCC), such as MMP1, MMP3, MMP9, YAP1, CYP1A1, and CYP1B1, was also observed." (PMID 36835505, 2023). "Circ-HIPK3 provides a new approach for the diagnosis and treatment of oral squamous cell carcinoma through miR-381-3p/YAP1." (PMID 34905439, 2021). "Ankyrin repeat-containing protein Kank1, when overexpressed, reduces the proliferation and increases the apoptosis of oral squamous cell carcinoma by reducing Yap1 and Taz protein expression." (PMID 33582842, 2021). "We showed that anaerobic bacteria impair tight junctions and promote cancer progression through YAP1 activation in oral squamous cell carcinomas (OSCCs)." (PMID 32064037, 2020). "In oral squamous cell carcinoma, nuclear YAP1 accumulation marked premalignant dysplastic regions of the oral epithelium and YAP1 promoted tumorigenic phenotypes and a transcriptional program associated with tumor progression." (PMID 29340043, 2017). "Comprehensive “-omics” interrogation of PDCs derived from one of these models revealed YAP1 as a putative biomarker for treatment response and survival in ~24% of oral squamous cell carcinoma." (PMID 28874669, 2017). "In oral squamous cell carcinoma cell lines, nuclear translocation of YAP1 correlated with the acquisition of cisplatin resistance." (PMID 29340043, 2017). "We found that Kallikrein-5 is necessary for PAR-2-mediated IL-8 release, YAP1-TAZ/TEAD activation, and matriptase-mediated oral squamous cell carcinoma migration." (PMID 34503205, 2021). "Moreover, we showed that Kallikrein-5 is necessary for PAR-2-mediated IL-8 release, YAP1-TAZ/TEAD activation, and matriptase-mediated oral squamous cell carcinoma migration." (PMID 34503205, 2021). "Similarly, it was reported that Yap1 formed complex with TEAD4 in the nuclei regulating the transcriptions of G1 arrest-related genes, such as CCND1, CCNE, CDK2, CDK4, and CDK6, in human oral squamous cell carcinomas." (PMID 31455378, 2019).